INS (insulin)
Diseases named in the same sentence as INS in open-access papers (continued):
Sharing a sentence is not in itself a finding about the gene and the disease.
Hyperinsulinemia (continued). "In addition to the decline in efficiency of insulin to promote glucose uptake and utilization, metabolic disorders of lipid are also an important manifestation of IR, and adipose tissue may compensate for hyperinsulinemia and result in hypertension." (PMID 38504161, 2024). "Hyperinsulinemia also impairs Aβ clearance, as both are degraded by insulin-degrading enzyme (IDE), and, during periods of high brain insulin, IDE will preferentially bind insulin." (PMID 38540695, 2024). "Adipocyte hypertrophy is promoted by hyperinsulinemia, and reducing CHO intake leads to decreased insulin secretion, potentially reducing adipocyte size." (PMID 39574523, 2024). "Our findings therefore reinforce the role of hyperinsulinism as the central mechanism of PBH and the importance of the BA-GLP-1-insulin axis." (PMID 38842763, 2024). "The empirical dietary index for hyperinsulinemia and IR (EDIH and EDIR) includes only food groups related to insulin biomarker responses." (PMID 36617570, 2023). "This implies that insulin inhibits the secretion of SHBG from the liver, resulting in high levels of free androgens, and explains why obese PCOS women with hyperinsulinemia have low SHBG levels." (PMID 37062827, 2023). "The fasting serum insulin level of HFD‐fed mice was 20‐ to 100‐fold higher than the ND group, confirming the expected hyperinsulinemia in our experimental condition." (PMID 37845194, 2023). "In PCOS women, insulin sensitivity was assessed by the glucose clamp technique and HMGB1 was measured at baseline and after acute hyperinsulinemia." (PMID 37256493, 2023). "When IGFBP-1 levels are low (in case of hyperinsulinemia), IGF-I bioactivity and IGF-I-mediated effects increase and supplement the actions of insulin." (PMID 36901984, 2023). "The mammalian target of the rapamycin (mTOR) pathway is coupled to the insulin/IGF-1 signaling pathway; thus, NAFLD has a high probability of occurring due to hyperinsulinemia." (PMID 36831551, 2023). "Paradoxically, overexpression of Gpx1 in mice induced a type 2 diabetes-like phenotype, featuring augmented glucose-stimulated insulin secretion (GSIS) and chronic hyperinsulinemia." (PMID 37107224, 2023). "Hyperinsulinemia is also seen in acute THPP attacks, and insulin release in response to oral glucose challenge is increased in patients with THPP, implying that insulin plays a role in the pathophysiology of hypokalemia in THPP." (PMID 37303055, 2023). "Hyperinsulinemia stimulates the production of VLDL triglycerides, and elevated insulin secretion raises the concentration of low-density lipoprotein cholesterol." (PMID 38068822, 2023). "In mice and rats with hyperinsulinemia induced by feeding an HFD, baicalin supplementation reduced blood insulin levels." (PMID 38203600, 2023). "Insulin can also raise basal and GnRH-stimulated testosterone concentrations in women with PCOS, and experimental hyperinsulinemia can boost androgen synthesis from isolated ovarian theca cells." (PMID 37854752, 2023). "Further study into the synergistic effect of insulin and IGF-1 to investigate IGF-1 response in hyperinsulinemia conditions can help understand the correlation between metabolic dysregulation and the IGF axis in cancer progression." (PMID 37373357, 2023). "Hyperinsulinemia has been reported to stimulate lipogenesis by activating SREBP, a process that inhibits IRS‐2 (Insulin receptor substrate 2) mediated insulin effects on glucose production." (PMID 37701187, 2023). "Pronounced fasting hyperinsulinemia was observed in HFD-fed mice, with significantly higher insulin (three-fold compared to REF, left) and C-peptide levels (two-fold compared to REF)." (PMID 38024380, 2023). "In this regard, some studies support that Aβ pathology, in combination with hyperinsulinemia, promotes higher levels of Aβ because IDE is much more selective for insulin than for Aβ." (PMID 37873836, 2023).
Hyperinsulinemia (continued). "Estradiol therapy prevents the effects of hyperinsulinemia on lipid metabolism in OVX female mice via inhibition of adipogenesis, lowering of hepatic TG, and improving insulin action on glucose metabolism." (PMID 37140372, 2023). "This was supported by the fact that serum fasting insulin and HOMA-IR were at the same level as in the HFHSD group, probably due to the major liraglutide effect of hyperinsulinemia." (PMID 37929025, 2023). "Insulin levels in WT males were substantially increased by HFD compared to CadKO, suggesting HFD-induced hyperinsulinemia, similar to previous results in AhRKO males." (PMID 37443781, 2023). "In contrast, the empirical lifestyle index for hyperinsulinemia and IR (ELIH and ELIR) is composed of physical activity (PA) and body mass index (BMI), and also food groups correlated with insulin biomarkers." (PMID 36617570, 2023). "When analyzing the relationship between hyperinsulinism and IR in PCOS, an essential and often overlooked aspect is the influence of the insulin clearance rate on insulin levels." (PMID 36834549, 2023). "Bulls of the HEP group had basal hyperinsulinemia with euglycemia, in contrast to LEP (serum insulin p < 0.001; plasma glucose p = 0.79)." (PMID 36003642, 2022). "Next, we observed that enoxacin-treated mice showed decreased serum insulin levels and HOMA-IR scores compared with mice in the vehicle group, further confirming the improvement of enoxacin on hyperinsulinemia." (PMID 36147348, 2022). "In the presence of hyperinsulinemia and high IGF levels, cancer cells upregulate insulin and IGF-1 receptors, resulting in the stimulation of signaling pathways that are closely related to mitogenesis, cell growth, and migration." (PMID 35802721, 2022). "We found insulin to increase THRSP mRNA expression 5- and 8-fold after 180 and 360 min of in vivo euglycemic hyperinsulinemia." (PMID 35715726, 2022). "Studies assessing β-cell function after PFAS exposure are limited to immortalized cell lines and generally point to increased insulin secretion, which is consistent with the in vivo data showing PFOS-induced hyperinsulinemia in mice." (PMID 35156417, 2022). "To establish an in vitro model of hyperinsulinemic conditions (i.e. in vitro hyperinsulinemia), we incubated differentiated mouse C2C12 myotubes for 16 h in a physiologically high insulin dose of 2 nM or supraphysiological high dose of 200 nM." (PMID 34921686, 2022). "The requirement of significantly higher amounts of endogenous insulin after 10 weeks of HF-dox diet, compared to measurements post 10 weeks of HFD in the control group, clearly implies HF induced hyperinsulinemia." (PMID 36012550, 2022). "Since we found hyperinsulinemia together with active AKT signaling in bronchial and vascular SMC in HFD, we next exposed bSMC to insulin." (PMID 35896539, 2022). "RF led to the synchronization of the circadian rhythms in the insulin of the hormones, glucagon-like peptide-1 (GLP-1), glucose-dependent insulinotropic polypeptide (GIP), and hyperinsulinemia in the light period." (PMID 36557311, 2022). "Despite the presence of hyperinsulinemia, women with PCOS are thought to have pancreatic β­cell dysfunction and also demonstrate decreased hepatic clearance of insulin." (PMID 35090546, 2022). "Taken together, these data indicate that the bile acid TUDCA attenuates hyperinsulinemia in Old mice by increasing liver IDE expression, and consequently, insulin clearance." (PMID 36564463, 2022). "The C-peptide levels obtained, reflecting insulin secretion, were significantly higher in the PCOS group than controls suggesting hyperinsulinemia in this population as expected." (PMID 35090546, 2022). "There is a wide literature base surrounding the use of insulin for inotropic support, with varying terminology used, such as glucose-insulin-potassium (GIK) therapy, hyperinsulinemia euglycemic therapy, and HDI therapy." (PMID 36042600, 2022).
Hyperinsulinemia (continued). "Hyperinsulinemia under NG conditions led to a significantly higher 4E-BP1(Thr37/46) phosphorylation both under basal conditions (p = 0.0006) and upon acute insulin stimulus (p = 0.0006)." (PMID 36386326, 2022). "We performed insulin treatment in both BV2 cell line and primary cultured microglia for 24 h in vitro, to mimic hyperinsulinemia condition in vivo." (PMID 36466168, 2022). "We demonstrated that prolonged physiological and supraphysiological hyperinsulinemia induced a reduction of AKT and ERK signaling and insulin‐stimulated glucose uptake." (PMID 34921686, 2022). "Hyperinsulinemia downregulates the number of insulin receptors in the BBB and, thus, attenuates insulin transport in the brain." (PMID 35661882, 2022). "Hyperinsulinemia is a typical symptom of T2DM, and studies have shown that exosome-derived miR-26a increases insulin sensitivity by enhancing insulin signaling, thereby reducing hyperinsulinemia." (PMID 36147580, 2022). "To investigate the effect of prolonged hyperinsulinemia on hepatic senescence, we exposed immortalized human hepatocytes (IHH cells) to insulin (20 and 100 nM) for 6, 24 or 72 h." (PMID 35872305, 2022). "As an initial approach to help elucidating the function of IDE on insulin metabolism in vivo, several laboratories developed mice with pancellular deletion of IDE (IDE-KO) and found age-dependent hyperinsulinemia and glucose intolerance." (PMID 35832432, 2022). "As a biguanide drug, metformin can ameliorate chronic anovulation and reactive hyperinsulinemia in PCOS patients by improving insulin sensitivity." (PMID 35564864, 2022). "TUDCA attenuated hyperinsulinemia and improved glucose homeostasis in aged mice, by enhancing liver insulin-degrading enzyme (IDE) expression and insulin clearance." (PMID 36564463, 2022). "Further, by in vitro study, the effects of hyperinsulinemia in primary microglia and BV2 cell line were determined after prolonged insulin treatment." (PMID 36466168, 2022). "Our results showed that D. lutheri has the potential to prevent abdominal obesity, hyperinsulinemia, hyperleptinemia, hypertriglyceridemia and NAFLD, as well as to improve glucose homeostasis and insulin sensitivity." (PMID 35807489, 2022). "Before starvation, both hyperinsulinemia groups had increased INSR phosphorylation, suggesting that there was continuous insulin signaling during the high insulin treatments." (PMID 34921686, 2022). "The rats in the T2DM group showed a highly significant (p < 0.01) increase in serum insulin compared to the CON group, indicating the development of hyperinsulinemia." (PMID 36362316, 2022). "Rather, IMQ-treatment affected plasma insulin concentration in a diet-dependent manner (PDiet*IMQ < 0.001), with HFD-fed IMQ-treated mice displaying significant hyperinsulinemia relative to untreated HFD-fed mice (p < 0.05 by post-hoc comparison)." (PMID 35874527, 2022). "Meanwhile, in vitro culture experiments confirmed the effect of insulin stimulation on IGF2/H19 in HepG2 cells, providing a potential explanation for intrauterine hyperinsulinemia directly affecting IGF2/H19 and subsequent impaired glucose metabolism." (PMID 35432202, 2022). "In obese pre-adolescents with hyperinsulinemia, metformin reduced BMI, BMI SDS, weight, HOMA-IR, fasting insulin, and fasting glucose." (PMID 36814831, 2022). "GTT and plasma insulin levels indicated that SKO mice showed impaired glucose tolerance and hyperinsulinemia, and AT transplantation significantly improve these two parameters." (PMID 33778025, 2021). "Additionally, despite upholding NGT, our centrally obese cohort were significantly insulin resistant and may have shown slight glucose intolerance as indicated by the greater post-meal glucose excursions and accompanying hyperinsulinemia compared to lean subjects." (PMID 34220720, 2021). "Metformin and hyperinsulinemia changed the expression of extracellular proteins (e.g. metformin: CTSL, EGFR, IL5, KLK3; insulin: IL4, IL15, PGC, SORL1)." (PMID 33690729, 2021).
Hyperinsulinemia (continued). "The BMI, T2DM, FBS, fasting serum insulin, HOMA-IR, HOMA-β, hyperinsulinemia, and insulin insensitivity increased significantly across ELIH score tertiles." (PMID 33985566, 2021). "Insulin can act on the IGF1-receptor, and hyperinsulinemia is thought to be a factor stimulating growth in idiopathic childhood obesity and in hypothalamic obesity in which GH is missing." (PMID 34002033, 2021). "Hyperinsulinemia, IR (as assessed by HOMA-IR) and insulin sensitivity (as assessed by QUICKI) were restored completely by treatment with nitrite, metformin, pioglitazone and ampicillin-neomycin combination in iNOS-/- mice." (PMID 35008623, 2021). "This was thought to be due to hyperinsulinemia found in MSG rats, since ovaries remain sensitive to insulin." (PMID 33953699, 2021). "Potential novel mechanisms for AD therapies in patients with peripheral hyperinsulinemia include reducing the load of insulin on IDE in the brain, either by increasing the affinity of IDE for Aβ or by decreasing brain insulin concentrations." (PMID 34497507, 2021). "Additionally, GLP-1s improve insulin-sensitivity which may decrease hyperinsulinemia over time." (PMID 33691751, 2021). "The long-lived rats (LS4 and LS5) show delayed hyperinsulinemia and reached to similar insulin levels as the short-lived rats (LS 1 and LS2) at 18 months of age, followed by ~35% decline of insulin at 24 months of age." (PMID 33744845, 2021). "Considering the positive association between fetal insulin levels and the incidence of later impaired glucose tolerance in the offspring, the correlation between AF EPO and offspring post-load PG concentrations in adulthood could be mediated by fetal hyperinsulinemia." (PMID 34777246, 2021). "Hyperinsulinemia disturbs the balance of the insulin–GH–IGF axis and shifts the insulin : GH ratio towards insulin and away from GH." (PMID 34360563, 2021). "microalga oil (rich in n-3 PUFA, DHA) against hyperinsulinemia in C57BL/6 J mice submitted to a hyperlipidic diet, suggesting the beneficial effects of n-3 LC-PUFA, and particularly DHA, in the improvement of insulin sensitivity." (PMID 33525643, 2021). "Insulin inhibits the production of IGFBP-1, a biomarker of decidualization, suggesting that hyperinsulinemia can affect the normal function of the endometrium, leading to failed embryo implantation and increased abortion rate." (PMID 34975540, 2021). "In addition, insulin may not improve the pathophysiologic features of women with GDM due to its risk of hyperinsulinemia which causes increased sodium reabsorption from the renal tubules, renin secretion, and sympathetic nervous activity." (PMID 34579668, 2021). "This relative hyperinsulinemia was concurred with lower NEFA levels and an unchanged insulin sensitivity suggesting an anti-lipolytic effect." (PMID 33435209, 2021). "Hyperinsulinemia elevated SUA levels by reducing the excretion of SUA and the accumulation of SUA products, and an increase in SUA also decreased glucose uptake by insulin." (PMID 34686184, 2021). "During hyperinsulinemia, IDE degrades insulin preferably to Aβ, promoting its oligomerization into insoluble aggregates." (PMID 34208833, 2021). "The compensatory increase in circulating insulin concentration has been attributed to an increase in pancreatic insulin secretion, but changes in hepatic insulin clearance are also contributing to the systemic hyperinsulinemia and may even be of greater importance, although widely debated." (PMID 33498493, 2021). "On NFD, fasting serum insulin levels were similar in male control and KPTIRKO mice; HFD resulted in hyperinsulinemia in both control and KPTIRKO mice to the same extent." (PMID 33400689, 2021). "Hyperinsulinemia is diagnosed using the oral glucose tolerance test, the glucose tolerance test (OGTT), and based on the values of the insulin sensitivity index." (PMID 35056318, 2021).
Hyperinsulinemia (continued). "Notably, the Disposition Index of the NMN + OLE group could have been higher than reported had insulin secretion not been suppressed by hyperinsulinemia (caused by decreased insulin clearance)." (PMID 34948019, 2021). "In the hypothetical case that IDE inhibition does impact circulating insulin levels, another facet relevant to the potential use of IDE inhibitors in clinical settings is the impact on hyperinsulinemia." (PMID 33668109, 2021). "Mecr mRNA was induced by insulin in cell culture, and was elevated in the liver of DIO mice in the presence hyperinsulinemia." (PMID 32440681, 2020). "Fasting serum insulin was increased by HFD feeding in male mice, while early exposure to NAC abrogated this hyperinsulinemia." (PMID 32183232, 2020). "Lipid and insulin synergistically increased FGF21 in healthy and insulin resistant women with PCOS; hyperinsulinemia suppressed FGF19 in controls." (PMID 33101202, 2020). "In this study, high serum insulin concentration was observed in rats after DHEA injection, indicating the occurrence of hyperinsulinemia." (PMID 32760272, 2020). "Finally, impaired insulin sensitivity and thereby increased insulin resistance due to the defects in the evolution of skeletal muscle tissue and its metabolism could contribute to the development of hyperinsulinemia and, consequently, increased sodium retention, inducing BP elevation." (PMID 32170412, 2020). "Previous research indicated that hyperinsulinemia reduces osteoblast activity via upregulation of TGF-β, and these results prompted us to investigate the potential role of TGF-β1 in insulin-mediated osteogenic differentiation of H-BMSCs." (PMID 32017705, 2020). "We did, however, observe a difference in fasting insulin levels, where C57BL/6J showed less pronounced hyperinsulinemia as a result of HFD compared to C57BL/6JBomTac and C57BL/6JRj." (PMID 32820201, 2020). "Furthermore, considering that leptin is secreted not only by adipose tissue but also by the gastric mucosa in response to food intake and insulin, hyperleptinemia could be regarded as a result of an increased production of gastric leptin elicited by hyperinsulinemia." (PMID 32092909, 2020). "Taken together, insulin stimulates brown adipocytes and regulates protein expression of complex I and complex II to maintain optimal utilization of substrates, balancing between maximizing ATP production and minimizing excessive ROS production, which could be the case in hyperinsulinemia." (PMID 33287103, 2020). "Insulin dysregulation plays a key role in EMS and hyperinsulinemia is probably the most important pathophysiologic component of insulin dysregulation in horses." (PMID 33302557, 2020). "Because these patients have hyperinsulinemia and IR, genes like MTNR1A/B related to insulin secretion possibly play a crucial role in PCOS progression." (PMID 32463080, 2020). "To identify the source of the hyperinsulinemia in TMBIM6−/− mice, we turned to pancreatic β cells which secrete insulin in response to changes in glucose levels." (PMID 32394396, 2020). "The insulin level was significantly increased in the HFD group, and evogliptin improved hyperinsulinemia." (PMID 32937958, 2020). "In male offspring, serum insulin concentrations in the NFCO-HF group were higher than the concentrations in all other groups (p < 0.05), suggesting that PWHF led to hyperinsulinemia." (PMID 31947955, 2020). "The hyperinsulinemia, together with elevated HOMA-IR and the results obtained from the GTT are reflective of defective insulin signaling." (PMID 32076010, 2020). "As expected, islet hypertrophy developed due to this chronic hyperinsulinemia, as found in HFD-fed male mice, and normalized in offspring of NAC-treated mice which had improved insulin sensitivity." (PMID 32183232, 2020).